MIAT (myocardial infarction associated transcript)
Diseases named in the same sentence as MIAT in open-access papers (continued):
Sharing a sentence is not in itself a finding about the gene and the disease.
tumor (continued). "Moreover, FOXM1 was positively correlated with MIAT expression in NSCLC tumor tissues." (PMID 32742195, 2020). "In addition, MIAT expression level was significantly different in the advanced tumor stage." (PMID 29228680, 2017). "Moreover, downregulation of MIAT inhibited the tumor growth in vivo." (PMID 29100300, 2017). "For example, lnc-TUG1, lnc-MMPA, lnc-MIAT, and lnc-ATB are lncRNAs whose expression levels are correlated with the state of the tumor immune microenvironment in HCC, suggesting their roles in regulating immune responses." (PMID 40352941, 2025). "Studies have indicated that the lncRNAs, MIAT, GABPB1, and PDPK2P influence tumor progression in HCC." (PMID 34876904, 2021). "To directly evaluate the correlation between the lncRNA MIAT/HMGB1/IL6 axis and tumor resistance in NPC patients, we collected samples from cisplatin-sensitive patients and the patients developed resistance." (PMID 34094941, 2021). "Gain- and loss-of-function experiments in cell lines and mouse xenograft models showed that MIAT promoted the proliferation, migration, and invasion of NSCLC cells in vitro and accelerated tumor growth in vivo." (PMID 32742195, 2020). "Our previous results indicated that MIAT competitively inhibited miR-150-5p, which in turn stimulated CDKN1B expression and eventually mediated its anti-tumor function." (PMID 32549789, 2020). "Conversely, TQ treatment resulted in the downregulation of several genes overexpressed in GBM cells, including potential oncogenes like AEBP1, MIAT, GHR, LMO1, ELF3, and genes involved in tumor proliferation and migration such as EPHA4, COL3A1, PCDH10, ROBO1, ADAMTS5, PCDH18, ST8SIA1." (PMID 39874307, 2025). "Interestingly, the analysis revealed that Meg3, MIAT and SNHG20 are primarily expressed by cells localized at the tumor edge or infiltrating the tumor core." (PMID 40527978, 2025). "We suggest that MIAT is involved in NBL progression and could be a candidate as a novel tumor marker for diagnosis and NBL treatment, especially for those with NMYC amplification." (PMID 33806217, 2021). "The mean tumor volume and weight were significantly reduced in the MIAT knockdown group compared with those in the negative control group." (PMID 32742195, 2020). "Previous studies have suggested that some lncRNAs may promote tumor progression through the dysregulation of tumor proliferation, apoptosis (e.g., MA-LINC1, HOTAIR), metastasis (e.g., MALAT1), and angiogenesis (e.g., MIAT, MEG3)." (PMID 32083005, 2020). "MIAT is a ceRNA for miR-155-5p, and knockdown of MIAT increased expression of the miR-155-5p target DUSP7 and inhibited MDA-MB-231 cell proliferation and xenograft tumor growth." (PMID 30545127, 2018). "To explore whether MIAT played a role in carcinogenesis, we first profiled the expression of MIAT in 60 pairs of NSCLC tissues (30 paired of adenocarcinoma and 30 paired of squamous) and paired adjacent non-tumor tissues." (PMID 29228680, 2017). "The qPCR data indicated that the expression level of MIAT in tumor tissues was significantly higher than that in the corresponding non-tumor tissues (mean dCT of tumor vs. normal tissue: 2.95 vs. 3.71, p = 0.0014)." (PMID 29228680, 2017). "MIAT silencing does not induce the inhibition of cell growth in the human non-tumor cell line HDFn." (PMID 33806217, 2021). "For instance, silencing lncRNAs such as MEG3, FTX, and MIAT in tumor-infiltrating myeloid or T cells, or enhancing expression of pro-inflammatory lncRNAs like NEAT1 or MIR17HG in T cells, may reduce immunosuppression, promote infiltration, and enhance activation of anti-tumor immunity." (PMID 40527978, 2025).
cardiovascular diseases (10 papers, 2013 to 2025). "MIAT is closely related to cardiovascular disease and is involved in the NF-κB pathway, promoting the expression of pro-inflammatory cytokines like IL-6 and TNF-α, and influencing the osteogenic differentiation of human adipose-derived and bone marrow mesenchymal stem cells." (PMID 39898106, 2025). "MIAT overexpression is also considered as a potent cardiovascular disease-promoting element." (PMID 36362982, 2022). "MIAT is another lncRNA with well-documented roles in cardiovascular diseases and cancer." (PMID 33329688, 2020). "In addition, lncRNAs are also emerging as biomarkers for cardiovascular diseases; for example, ANRIL, KCNQ1OT1, and MIAT are markers of left ventricular dysfunction in postmyocardial infarction." (PMID 35392816, 2022). "Besides H19 and MIAT, LINC00305 is another lncRNA with a potential role in cardiovascular diseases." (PMID 33329688, 2020).
heart diseases (4 papers, 2020 to 2025). "Given that MIAT upregulation is also implicated in other forms of heart disease, the maladaptive role of MIAT in CMs may be relevant across various stress settings." (PMID 39979325, 2025). "This nuclear lncRNA (NCBI accession no.: NR_003491) is widely expressed in endothelial cells, Müller glia and neurons, but dysregulation of MIAT is associated with various heart diseases and nervous system tumors, as it is involved in the maintenance of proper microvascular and nervous function." (PMID 34026614, 2021). "An abnormally high expression pattern of MIAT has been documented in various heart diseases." (PMID 33819189, 2021).
neurodegenerative disease (3 papers, 2018 to 2024). A disorder of the central nervous system characterized by gradual and progressive loss of neural tissue and neurologic function. "Among the abundant lncRNAs that were upregulated by exposing the cells to Sin1 were those implicated in redox homeostasis, energy metabolism, and neurodegenerative diseases (e.g., MALAT1, MIAT, GABPB1-AS1, NEAT1, MIAT, GABPB1-AS1, and HAND2-AS1)." (PMID 36412908, 2022). "By establishing a PD model, researchers found that MIAT may be involved in the pathogenesis of this neurodegenerative disease at both the molecular and cellular levels, bringing compelling evidence." (PMID 39456775, 2024).
adenocarcinoma (2 papers, 2017 to 2020). A common cancer characterized by the presence of malignant glandular cells. "RT-qPCR results revealed that MIAT expression was significantly increased in GC tissue samples (adenocarcinoma) as compared with paratumor tissues." (PMID 33154765, 2020).
infection (2 papers, 2019 to 2021). The state of being infected such as from the introduction of a foreign agent such as serum, vaccine, antigenic substance or organism. "Increased expression of NEAT1, MALAT1, EGOT, PVT1, MIAT has been also observed in infection with other viruses." (PMID 34940755, 2021).
inflammation (2 papers, 2020). Aberrant reaction of the microcirculation characterized by movement of fluid and leukocytes from the blood into extravascular tissues. "In summary, our data revealed that knockdown of MIAT protected against LPS-induced pulmonary inflammation and injury, which was mediated by miR-147a/NKAP axis." (PMID 33318298, 2020). "Together, silencing of MIAT alleviates LPS-induced pulmonary inflammation and injury via regulating miR-147a/NKAP axis." (PMID 33318298, 2020).
hematological cancers (1 paper, 2022). "In hematological cancers, such as AML, the overexpressed MIAT in AML functions as a sponge to inhibit miRNA-495 (miR-495) and abrogate the suppression of carcinogenesis." (PMID 35432537, 2022).
infectious disease (1 paper, 2024). A disorder directly resulting from the presence and activity of a microbial, viral, or parasitic agent in humans. "With studies showing MIAT’s involvement in the activation of inflammatory response in various diseases, lncRNA-MIAT has attracted the attention of the researchers in the field of infectious diseases." (PMID 39770858, 2024).
metabolic disease (1 paper, 2021). A congenital disorder (due to inherited enzyme abnormality) or acquired (due to failure of a metabolically important organ) disorder resulting from an abnormal metabolic process. "Additionally, MIAT overexpression in endothelial cells has been reported to upregulate VEGF levels by inhibiting miR-150-5p, which suggests that there is an interplay among MIAT, miR-150-5p, and VEGF to promote angiogenesis, which is related to metabolic diseases." (PMID 34298896, 2021).
neurological diseases (1 paper, 2024). "Overall, MIAT might act as an important regulator in a variety of neurological diseases, especially in the development of IS." (PMID 38383415, 2024). "The role of MIAT in neurological diseases is reportedly regulated by miRNAs." (PMID 38383415, 2024).
MIAT also shares sentences with these, for which no sentence is quoted: acute myocardial infarction (2 papers); arteriopathy (2); hypertrophy (2); major depressive disorder (2); psychiatric diseases (2); renal fibrosis (2); retinopathy (2); acute kidney injury (1); age (1); amyloid (1); B-cell acute lymphocytic leukemias (1); benign tumors (1); beta thalassemia (1); blood cancers (1); brain tumors (1); Burkitt lymphoma (1); chronic myeloid leukemia (1); cognitive decline (1); cognitive disorder (1); colitis (1); diffuse large B-cell lymphoma (1); follicular lymphoma (1); glaucoma (1); laryngeal carcinoma (1); metastatic disease (1); Nephropathy (1); nervous system tumors (1); neurovascular disorder (1); oligoastrocytoma (1); oligodendroglioma (1).
A further 12 diseases each share a sentence with MIAT in 1 paper.